ESR2 (estrogen receptor 2)
Diseases named in the same sentence as ESR2 in open-access papers (continued):
Sharing a sentence is not in itself a finding about the gene and the disease.
Anxiety (84 papers, 2010 to 2026). Intense feelings of nervousness, tension, or panic often arise in response to interpersonal stresses. "Moreover, estradiol was found to be a potential novel therapeutic tool for anxiety, something that underlines the important role of estrogen receptors (ESR1/ESR2) in anxiety regulation." (PMID 40508224, 2025). "In addition, there is evidence that ESR2 are linked to anxiety disorders and can act as modulators of anxiety-like behavior." (PMID 30544539, 2018). "In behavioral trials, such as light- and dark-box and open-field tests in animals, it was shown that the activation of the estrogen receptors ESR1 and ESR2 is closely related to increased anxiety in rodents." (PMID 38257381, 2024). "A study analyzed the anxious behavior resulting from the deletion of genes involved in anxiety to their brain expression in mice, with one of them being the ESR2 gene." (PMID 30544539, 2018). "ESR1 is critical for reproduction function, and ESR2 is critically involved in regulating reproductive behaviors, brain development and procession of emotional behavior (anxiety-related behavior e.g.)." (PMID 21303561, 2011). "However, it was previously shown that Esr2+/− behave in a similar manner as wild-type mice in the elevated plus-mice, a test assessing anxiety-like behaviors." (PMID 30863326, 2019). "An investigation noted that, for the ERβ gene ESR2, the SNP rs1256049 was related with a greater incidence of generalized anxiety disorder in older women, while the female ERβ knockout mice increased anxiety-like behaviors." (PMID 30544539, 2018). "Male mice did not exhibit significant effects related to anxiety in the EPM, but molecular analysis showed up-regulation of estrogen receptor 2 (ESR2; 20 and 200 μg/kg/day groups) and dopamine receptor 1 (20 μg/kg/day and 750 mg/kg/day groups) in the amygdala but not in the hippocampus." (PMID 40469448, 2025).
breast tumors (71 papers, 2001 to 2025). "Estrogen receptor beta (ERβ), encoded by the ESR2 gene, is a steroid nuclear hormone receptor expressed in up to 20% of TN breast tumors." (PMID 40647431, 2025). "However, a recent study has probed over 3000 primary breast tumors for RNA levels of ESR2 and found that, although its overall expression is low, ESR2 is associated with better overall survival." (PMID 37711895, 2023). "Our findings suggest that ESR expression, particularly ESR2 expression, may relate to immune gene regulations in luminal breast tumors and this association may explain the previously reported favorable prognosis associated with ERβ expression." (PMID 31856876, 2019). "Analysis of the TCGA breast tumors confirmed that ESR2 was generally expressed at low levels, but higher in ERα-negative PAM50 subtypes." (PMID 35304506, 2022). "In another study, ESR2 was methylated in 64% of breast tumors and 12% of adjacent normal tissues serving as control." (PMID 28403857, 2017). "Notably, Kaplan-Meier survival analysis revealed that high levels of ESR2 in patients with invasive breast carcinoma, demonstrate a significantly lower overall survival, as compared to breast tumors with low ESR2 expression." (PMID 35719919, 2022).
lung cancer (64 papers, 2010 to 2025). A malignant neoplasm involving the lung. "Several studies have shown that the estrogen receptor beta (ESR2) appeared in many tumors, including lung cancer, wherein ESR2 and interleukin 6 receptor (IL-6R) interacts to mediate lung cancer progression." (PMID 34497656, 2021). "In the past, the prognostic value of ESR2 expression in other human malignancies, including breast, ovarian, bladder, prostate and lung cancer, was controversially discussed further supporting a strong context dependency." (PMID 28166815, 2017). "This assumption is further supported by recent reports demonstrating that the presence of ESR2 modulates response to several therapeutic agents in breast and lung cancer cells." (PMID 28166815, 2017). "However, the role of ESR2 in lung cancer remains uncertain, and the oncogenic role of ESR2 is a current topic in research." (PMID 39695171, 2024). "According to previous studies, ESR2 is the predominant oestrogen receptor in lung cancer." (PMID 39695171, 2024). "For example, ESR2 (degree = 13), also known as ERβ, it could promote lung cancer invasion via increasing CXCR4 expression." (PMID 36339610, 2022). "The role of estrogen receptors in lung cancer is not as clear, but lung cancer is considered estrogen positive, with predominant ESR2 expression, and in females ESR2 is associated with a worse prognosis." (PMID 35924166, 2022). "Previous gene expression screening suggested estrogen receptor expression may be increased by FZD9 loss and alterations in estrogen receptors have been associated with lung cancer, so we measured expression of estrogen receptor α (ESR1) and β (ESR2)." (PMID 35924166, 2022). "In the past, there were few studies on the relationship between ESR2 and lung cancer." (PMID 33868436, 2021). "The single nucleotide polymorphisms of ESR2 are closely related to lung cancer in nonsmoking women, and studies have shown that nonsmoking women in Asia have a higher mutation rate of the EGFR gene." (PMID 33868436, 2021). "Previous studies have shown that ESR2 is involved in the progression of NSCLC and is the predominant form in lung cancer." (PMID 39695171, 2024).
colorectal cancer (47 papers, 2011 to 2025). A primary or metastatic malignant neoplasm that affects the colon or rectum. "As the prognostic significance of ESR1 in an eight genes assessment model in liver cancer, and ER‐β expression in colorectal cancer and ESR2 polymorphisms in advanced gastric cancer." (PMID 32536040, 2020). "A significant positive association with colorectal cancer risk was found with average number of the CA repeats in ESR2 (OR per unit increase in average repeat number =1.05, 95% CI 1.01 - 1.10, p =0.02)." (PMID 25376484, 2014). "In summary, alleles with higher numbers of ESR2 CA repeats are potentially associated with a small increase in colorectal cancer risk." (PMID 25376484, 2014). "In the present population-based case-control study, the average number of CA repeats in ESR2 was positively associated with colorectal cancer risk." (PMID 25376484, 2014). "Further large epidemiological studies as well as functional studies are needed to elucidate the role of ESR2 and AR polymorphisms in colorectal cancer development and prognosis." (PMID 25376484, 2014). "We therefore assessed the association of repeat polymorphisms in the estrogen receptor β gene (ESR2) and the androgen receptor gene (AR) with colorectal cancer risk and prognosis." (PMID 25376484, 2014). "With the present study, we aimed to investigate the association between the AR CAG and ESR2 CA repeat polymorphism and colorectal cancer risk and prognosis, also stratified by the tumoural expression of ESR2." (PMID 25376484, 2014). "Higher numbers of ESR2 CA repeats are potentially associated with a small increase in colorectal cancer risk." (PMID 25376484, 2014). "Although the limitation of our study was the analysis of the gene expression levels in a set of FFEP specimens, our data pointed out that the deregulation of ESR2 isoform variants may be associated with colorectal cancer progression." (PMID 29132333, 2017). "Therefore, genetic variation in ESR2 and AR may affect the action of sex steroids on colonic epithelium and consequently influence the colorectal cancer susceptibility and prognosis." (PMID 25376484, 2014). "Taking into account the reported associations and given that the expression of ESR2 in tumour tissue of colorectal cancer patients has been associated with overall survival, it cannot be ruled out that genetic variation influencing ESR2 expression plays a role in colorectal cancer prognosis." (PMID 25376484, 2014). "Few candidate-gene studies have evaluated variation in hormone receptors (ESR1, ESR2, PGR) in relation to colorectal cancer risk." (PMID 21627810, 2011). "We observed little support for an association of gene variants in hormone receptors (ESR1, ESR2, PGR) and active estrogen synthesizers (HSD17B1, HSD17B2, and HSD17B4) with colorectal cancer risk among postmenopausal women of European descent." (PMID 21627810, 2011). "While previous studies have shown that ACIN1 may activate proapoptotic signaling pathways in colorectal cancer, we hypothesize that it may work synergistically together with ESR2, a known tumor suppressor in CRC." (PMID 39201394, 2024). "Since ESR2 and NDRG2 are markedly low in colorectal cancer, enhancing ESR2 by blocking UBE3A-mediated degradation of ESR2 could offer a therapeutic target for CRC." (PMID 37541588, 2023). "Moreover, the low ESR2 expression level was confirmed from four datasets in colorectal cancer and hepatocellular cancer." (PMID 32536040, 2020). "The average number of ESR2 CA repeats was associated with a small 5% increase in colorectal cancer risk (OR = 1.05, 95% CI 1.01-1.10) without significant heterogeneity according to gender or tumoural ESR2 expression." (PMID 25376484, 2014).
colorectal cancer (continued). "Owing to a similar chemical structure as endogenous estrogen, flavonoid phytoestrogens can bind to ESR2, the predominant estrogen receptor expressed in the colon mucosa, and activate estrogen-responsive pathways, which play an important role in tumorigenesis and progression of colorectal cancer." (PMID 30871032, 2019). "However, our results do not support a differential association of the ESR2 CA repeat with colorectal cancer risk or prognosis according to ESR2 status." (PMID 25376484, 2014). "Cervical and colorectal cancers showed weak to moderate membranous ESR2 protein expression, and most remaining cancer types were ESR2-negative." (PMID 37240447, 2023).
Obesity (47 papers, 2007 to 2025). Accumulation of substantial excess body fat. "ESR1:ESR2 gene expression was negatively associated with age, obesity markers (eg, BMI, WHR, body fat percentage), and fasting glucose." (PMID 39833659, 2025). "In contrast, data on the influence of weight status on ESR2 mRNA levels in adipose tissue are scarce; however, our study suggested that the obesity and weight-loss-related changes in ESR2 expression in SAT mimic those observed in the case of ESR1." (PMID 35682668, 2022). "Polymorphisms in genes encoding ERα (ESR1) and ERβ (ESR2) were associated with the risk of obesity and metabolic syndrome; however, the associations were population-specific." (PMID 35682668, 2022). "Future studies with larger cohorts are important to investigate the effect of metformin treatment on ESR2 expression and its associations with obesity and insulin resistance." (PMID 35856485, 2022). "Even though the association between the decline in ESR1 and ESR2 expression in adipose tissue and the incidence of obesity has been postulated for some time, little is still known about the molecular mechanisms leading to these phenomena." (PMID 35682668, 2022). "We here demonstrated associations of ESR1 and ESR2 polymorphisms with MetS and related components, especially obesity, and lipid and glucose metabolism, in postmenopausal Chinese Han females." (PMID 30217154, 2018). "An additional keyword search pointed to new clinical data showing that an ESR2 deficiency can reduce the risk of obesity after ovariectomy." (PMID 26694100, 2015). "In this report we analyse ESR1 and ESR2 gene single nucleotide polymorphisms (SNPs) for association with obesity." (PMID 18053221, 2007). "Five ESR2 SNPs displayed nominal significant allelic association with obesity in women and one in men." (PMID 18053221, 2007). "In this report we analyse polymorphisms covering most of the common haplotype variation in the ESR1 and ESR2 genes for association with obesity in two large cohorts of Swedish Caucasians." (PMID 18053221, 2007). "We selected miRNAs for this analysis that met three primary criteria: (i) a predicted in silico interaction with ESR1 or ESR2 mRNA, (ii) a suggested role in the regulation of ESR1 or ESR2 expression in vivo, and (iii) an altered expression in adipose tissue in the course of obesity or weight loss." (PMID 35682668, 2022). "One may wonder about the primary phenomenon: whether excess adiposity causes a decrease in ESR1 and ESR2 expression or whether their decreased levels predispose humans to obesity." (PMID 35682668, 2022). "Furthermore, when associations between expression of ESR2 and markers of obesity and insulin resistance were assessed in control subjects and metformin-treated patients with T2D, few correlations were significant and only in males." (PMID 35856485, 2022). "It has been shown that obesity-associated systemic factors reduce ESR2 expression, which may function as a compensatory mechanism to limit lipogenesis and lipolysis in adipose tissue." (PMID 35856485, 2022). "In sample 1, two ESR2 SNPs were associated with obesity with nominal P value < 0.01." (PMID 18053221, 2007). "Two ESR2 SNPs, rs7154455 and rs3020450 were associated with obesity with nominal P value < 0.01." (PMID 18053221, 2007). "ESR2 SNP rs4986938 was associated with obesity in men only, nominal P value 0.05." (PMID 18053221, 2007). "We suggest that elevated aromatase content in SAT, together with altered ESR1/ESR2 balance, in men with obesity contributes to the development of insulin resistance and T2D." (PMID 39833659, 2025). "In this study, we aimed to investigate the role of ARO, ESR1, and ESR2 in SAT from men with obesity and T2D." (PMID 39833659, 2025). "ESR1:ESR2 gene expression ratio was lower in participants with obesity compared to lean individuals (P < .05)." (PMID 39833659, 2025).
Obesity (continued). "Obesity was associated with a decrease in mRNA levels of both ERs in SAT (p < 0.0001) and ESR2 in VAT (p = 0.0001), while weight loss increased ESR transcription (p < 0.0001)." (PMID 35682668, 2022). "What distinguished the obesity-related changes in ESR2 expression compared with ESR1 in our study was that the decrease in ESR2 gene expression referred to visceral and subcutaneous adipose tissue depots." (PMID 35682668, 2022). "We found that obesity was associated with a significant decrease in ESR1 and ESR2 mRNA levels in adipose tissue; however, the effect was depot- and gender-specific." (PMID 35682668, 2022). "Nonetheless to respond the all the causes of dyslipidemia and obesity we are also investigating other SNPs that have been previously asssociated to this illness, like SNPs on genes such as CYP19A1, ESR2 and PGR." (PMID 28199328, 2017). "Genes previously-reported to be associated with obesity and that reside within marker intervals at our peak LOD scores include GHRL, PPARG, HTR2A and ESR2." (PMID 21062459, 2010). "Common ESR1 gene alleles are unlikely to contribute to obesity in women, whereas a minor importance of ESR2 on severe obesity cannot be excluded." (PMID 18053221, 2007). "This study explored alterations in ARO, ESR1, and ESR2 in men with obesity or T2D." (PMID 39833659, 2025). "Therefore, further studies, including single-cell analyses, are required to verify the role of DNA methylation in regulating obesity and weight-loss-associated changes in ESR1 and ESR2 transcriptional activity in adipose tissue." (PMID 35682668, 2022). "These hub genes were associated with progression of obesity associated type 2 diabetes mellitus and first five (CEBPD, TP73, ESR2, TAB1 and MAP 3K5) of them might be linked with targeted therapy." (PMID 33902539, 2021). "The hub genes CEBPD, TP73, ESR2, TAB1, MAP 3K5, FN1, UBD, RUNX1, PIK3R2 and TNF, which might play an essential role in obesity associated type 2 diabetes mellitus was further screened." (PMID 33902539, 2021). "Furthermore, our cohort of men was too small to exclude a male-specific impact of ESR1 and ESR2 on obesity." (PMID 18053221, 2007). "We assessed whether there was an association between the gene expression of ARO, ESR1, and ESR2 in the combined cohorts 1 and 2, which included men with or without obesity or T2D." (PMID 39833659, 2025). "Interestingly, in the obese patients after weight loss, the ESR1/ESR2 mRNA ratio in SAT and VAT remained elevated, suggesting that obesity may leave a permanent mark on adipose tissue function." (PMID 35682668, 2022). "One can suppose that the obesity-induced upregulation of hsa-miR-495-3p in SAT may neutralize the beneficial influence of estrogen (via interference with ESR2 mRNA) and promote adipose tissue inflammation and the development of metabolic complications of obesity." (PMID 35682668, 2022). "After demonstrating that exposure to obesity-associated systemic factors inhibits SKBR3 cell ERβ expression and modulates ERβ target genes, we next examined whether these effects occur via the regulation of ESR2 transcription or through a post-transcriptional mechanism." (PMID 26709918, 2015). "In this study, we investigated the expression of ARO, ESR1, and ESR2 in SAT and VAT from men with varying degrees of obesity and T2D, as well as the effects of the sex steroids E2 and testosterone on adipocyte glucose uptake." (PMID 39833659, 2025). "The common targets of obesity, T2DM, and AS are estrogen receptor 2 (ESR2), androgen receptor (AR), CYP19A1, NR3C1, SRC, and arachidonate 5-lipoxygenase (ALOX5)." (PMID 39575382, 2024). "Gene and protein expression of ARO, ESR1, and ESR2 in SAT from participants with or without obesity (matched for age) or T2D (matched for age and BMI) was first assessed." (PMID 39833659, 2025).
Obesity (continued). "ESR1 gene expression levels were lower in men with obesity than in lean men and men with overweight (P < .05), while ESR2 gene expression levels were not affected by obesity status." (PMID 39833659, 2025). "In the postmenopausal group, as in the men, obesity had no impact on the ESR2 mRNA concentrations in VAT and SAT." (PMID 35682668, 2022). "In order to determine whether epigenetic modifications play a role in regulating obesity-related changes in ESR1 and ESR2 mRNA levels in adipose tissues, we investigated the methylation status of the regulatory regions of these two genes." (PMID 35682668, 2022). "Neither ESR1 nor ESR2 protein levels were affected by obesity status." (PMID 39833659, 2025). "Given the role of epigenetic mechanisms in regulating the expression of genes encoding ERs in estrogen-dependent tumors, we investigated whether DNA methylation and miRNA interference participated in the observed obesity-induced decrease in the ESR1 and ESR2 mRNA levels in adipose tissue." (PMID 35682668, 2022). "Subcutaneous adipose tissue (SAT) from men with or without obesity or T2D was analyzed for ARO, ESR1, and ESR2 gene and protein expression." (PMID 39833659, 2025). "We also show that ESR1 and ESR1:ESR2 ratio, but not ESR2, gene expression levels in SAT are decreased in men with obesity." (PMID 39833659, 2025). "The obesity-related changes in ESR1 and ESR2 expression in adipose tissues did not correlate with the methylation status of the regulatory regions in these two genes." (PMID 35682668, 2022). "Men with obesity had lower levels of ESR1 and ESR1:ESR2 ratio, but not ESR2." (PMID 39833659, 2025).